IL1B (interleukin 1 beta)
Diseases named in the same sentence as IL1B in open-access papers (continued):
Sharing a sentence is not in itself a finding about the gene and the disease.
infection (continued). "Consistent with this, iSCs internalize and respond rapidly to in vitro infection with the flagellated bacterium Salmonella typhimurium, increasing their expression of IL-1β and IL-33 at both the mRNA and protein level, with this sensing dependent on RIPK2/p38MAPK signaling." (PMID 24137162, 2013). "IL-1β and IL-17 were expressed in similar amounts in mice infected with K. rhinoscleromatis, Kp52.145 or Kp110 the first 3 days of infection and then decreased at day 5 in Kp110-infection because the bacteria were being cleared from the organ." (PMID 23554169, 2013). "In addition, mutants lacking FLT_0325 also induce higher levels of caspase-1 activation dependent on Aim2 and Tlr2 and secretion of IL-1β dependent on Tlr2, Aim2, and Nlrp3 in the early periods of infection." (PMID 24324933, 2013). "In contrast, in another study, the same group demonstrated that PBMCs with the variant allele do not produce more IL-1β in comparison to the normal allele upon infection with M. tuberculosis." (PMID 24273538, 2013). "Infection of macrophages or dendritic cells deficient in NLRP3 with Mtb does not induce secretion of IL-1β or IL-18." (PMID 24130966, 2013). "IL-1β was also elevated in the intestine with a peak at 3–6 days post infection (dpi)." (PMID 23935505, 2013). "One plausible explanation for lower levels of IL-12p70, IL-10, IL-1β, and GM-CSF may be attributed to differences in the time kinetics for their optimum secretion during the infection process." (PMID 23766556, 2013). "Indeed, lowering the stringency of the microarray analysis allowed the identification of over 70 genes, including several genes known to be associated with the mammary gland response to infection, e.g. SOD2, IL1B, LTF, S100A8 and S100A12." (PMID 23324411, 2013). "Indeed, when similar infectious doses are applied, although infection with virulent Kp52.145 is lethal, the cytokines IL-1β, IL-6, and IL-17 and the chemokines CCL2, CCL3 and CCL4 are produced in similar manner." (PMID 23554169, 2013). "The correlation coefficients (R2) for TNF-α, IL-1β, IL-6 and IL-12 with percent apoptosis were 0.906, 0.864, 0.879 and 0.890 respectively (P<0.05) on 5th day and 0.830, 0.669, 0.639 and 0.846 respectively (P<0.05) on 6th day of infection." (PMID 23667550, 2013). "However, to control an acute infection by virulent M. tuberculosis the amplification loop provided by IL-1β through upregulation of TNF in infected macrophages in vitro and here in vivo, seems to be necessary." (PMID 25400917, 2013). "Importantly, the level of IL-1β in the bronchoalveolar lavage fluid (BALF) 24 hours post-infection is significantly attenuated in Asc−/− mice infected with ΔflaA Lp." (PMID 23762026, 2013). "To determine the relative contributions of IL-1α and IL-1β to neutrophil recruitment and bacterial clearance during L. pneumophila infection, we utilized neutralizing antibodies to selectively block either IL-1α or IL-1β prior to infection." (PMID 23762026, 2013). "We previously hypothesized that MVAΔIL-1βR’s inability to neutralize IL-1β upon infection may lead to improved functionality of DCs, and thus better T cell memory responses." (PMID 23356675, 2013). "Importantly, inflammatory burst induced by S. flexneri, associated with bacterial invasion and dissemination as well as resolution of infection by a competent host, requires caspase-1, IL-1β, and IL-18." (PMID 24324933, 2013). "In alveolar epithelial cells infection of Moraxella catarrhalis was shown to induce monocyte adhesion, transepithelial migration and superoxidegeneration, whereas stimulation with lipopolysaccharide (LPS), TNFα, IL-1β or IFN-γ induced adhesion or TM." (PMID 23448224, 2013). "Western blot analysis reaffirmed that peritoneal macrophages from WT but not Nlrp3−/− mice secreted mature IL-1β to cell supernatants after infection with C. rodentium, and as well, that administration of exogenous IL-1β induced maturation of the cytokine in uninfected WT macrophages." (PMID 24312491, 2013).
infection (continued). "In addition the reduced lung levels of IL-6, IL-1β as well as neutrophil influx upon infection under Panobacumab treatment would indicate that the reduction of the bacterial load by Panobacumab resulted in an overall attenuated pro-inflammatory response." (PMID 24023870, 2013). "Although we did not observe typical granuloma formation in the tissue sections, we did observe significant neutrophil infiltration, representative of an early stage of inflammation, and the increase in IL-1β content and infection duration are important mediators of the inflammatory response." (PMID 24098654, 2013). "Although treatments for RA targeting TNFα or IL-1β have proved effective for many patients, there are still some problems to be solved – such as the nonuniversal adequacy and maintenance of response and risks of adverse effects like infection and malignancy." (PMID 24314202, 2013). "Notably, at days 1 to 3, rUSSR-NS1 1918 infection resulted in a significantly lower IL-1β response than rUSSR-NS PR8 infection, even though viral load was similar between the two groups of infected ferrets." (PMID 23592984, 2013). "The products of the IL1A and IL1B genes are also involved in innate responses including up-regulation of endothelial adhesins for neutrophils, induction of acute-phase proteins, and early recruitment of inflammatory cells to the sites of infection." (PMID 23690962, 2013). "In our birth cohort, infants with high levels of TNF-α and IL-1β at birth persist in this pattern during infancy, and these intrinsically higher levels might act early during an infection to control parasite density." (PMID 24130857, 2013). "Infection with Ft triggered a predominantly AIM2-dependent IL-1β response." (PMID 23554897, 2013). "IL-1β was reduced in the lungs of SP-A-/- mice following PAK infection." (PMID 24312669, 2013). "TNF-α, however, is just one of the cytokines released in response to L. monocytogenes with other pro-inflammatory cytokines, including IL-6 and IL-1β, released during infection in vivo, and mast cells have been shown to secrete these in response to L. monocytogenes in vitro." (PMID 23460827, 2013). "Thus, both infection-independent phagocytic-mediated uptake of HCV virions as well as endosomal acidification are involved in IL-1β stimulation in macrophages." (PMID 23633957, 2013). "Concurrently, Dixit and colleagues reported the generation of the first inflammasome knockouts, namely mice deficient in IPAF (NLRC4) or the adaptor ASC, and showed that macrophages from these mice had a defect in IL-1β production following infection with flagellated bacteria." (PMID 24137163, 2013). "Expression levels of interleukin (IL)-4, IL-10, IL-13 and tumor necrosis factor (TNF)-α were significantly up-regulated while interferon (IFN)-α, IFN-β, IFN-γ, IL-1β,IL-2, IL-3, IL-15, IL-17F, IL-18 and colony-stimulating factor (CSF)-1 were markedly decreased in PBMCs at all stages of infection." (PMID 24358317, 2013). "Enhanced transcription of IL1B in response to Salmonella was robustly observed across stromal cells from six individual patients and averaged an ∼10-fold increase over uninfected cells after 6 h of infection (p < 0.05)." (PMID 24137162, 2013). "During microbial infection, IL-1β production is induced by cellular sensing of pathogen-associated molecular pattern (PAMP) motifs within microbial macromolecules and/or by metabolic products that accumulate from infection." (PMID 23633957, 2013). "Overall, st2−/− mice tended to have higher mediator levels in lungs than WT mice; especially 14 days after infection with influenza A modest but statistically significant differences were seen in pulmonary IL-6 (P<0.001), IL-1β (P<0.01), KC (P<0.05), IL-10 (P<0.05) and IL-33 (P<0.05) concentrations." (PMID 23483993, 2013). "Our results showed that SGE could decrease the pro-inflammatory cytokine TNF-α and IL-1β mRNA levels in lung 5 days after infection." (PMID 23227098, 2012).
infection (continued). "Using this in vitro infection, neutrophils from mice deficient in TLR2, NOD2 or FPR1 produced significantly less IL-1β protein (40, 43 and 37 percent decrease, respectively) in response to S. aureus, suggesting that activation of TLR2, NOD2 and FPR1 promoted neutrophil production of IL-1β." (PMID 23209417, 2012). "There was a maximum increase in IL-1β levels by 110-folds which was observed on 5 d post infection." (PMID 22393394, 2012). "IL-1β triggers activation of nuclear factor κB (NF-κB) and MKKs, and it initiates systemic and local inflammatory responses that facilitate the recruitment of inflammatory cells to the site of infection." (PMID 22792226, 2012). "It is therefore possible that the B. anthracis spores and the LT may present distinct agonists which engage different signaling pathways at different timepoints during infection to induce the production of IL-1β." (PMID 23162703, 2012). "The concentrations of IL-1β and IL-8 were significantly (P = 0.045 for IL-1β at day 16; P = 0.0257 and P = 0.010 for IL-8 at day 12 and 20 respectively) higher in wild type-infected compared with ∆Vpr-infected culture at infection phase." (PMID 22727020, 2012). "NH4Cl treatment reduced IL-1β release from both OT infected and ATP treated macrophages in a dose-dependent manner, indicating that endo/phagosomal maturation is required for IL-1β secretion upon OT infection." (PMID 22723924, 2012). "The importance of the negative regulation of the inflammasome in neutrophils may be related to their abundant accumulation at the site of infection, where the amount of IL-1β release may need to be finely controlled." (PMID 22496641, 2012). "These processes are driven by IL-1α and IL-1β which signal through the IL-1R1 (IL-1Rα) and MyD88 to drive downstream NF-κB activation and subsequent expression of genes whose products regulate the immune response to infection." (PMID 23209411, 2012). "As seen during the natural infection, Shigella infection of rabbit ileal loops led to a large increase in mRNA abundance for the pro-inflammatory cytokines IL-1β, TNF- α, IL-6, IL-4, IFN-γ and IL-8, highlighting the similar cytokine response elicited in the two systems." (PMID 22675469, 2012). "Next, BMDMs were primed with LPS and challenged with ATP, or live or inactivated OT to determine whether OT infection provides a second signal for the processing and release of IL-1β." (PMID 22723924, 2012). "Furthermore, recent observations show that early-life infections can alter the threshold of IL-1β production in the hippocampus via long-lasting priming of microglia." (PMID 22738332, 2012). "This is also suggested by the release of lysosomal content into the medium, as indicated by the increased β-galactosidase activity upon infection of macrophages with B. cenocepacia, which agrees with a recent report showing that IL-1β secretion is accompanied by lysosome exocytosis." (PMID 22848580, 2012). "Both IL-1α and IL-1β are regarded as pro-inflammatory cytokines, but IL-1β rather than IL-1α has been more commonly associated with symptoms such as weight loss and fever that are induced by infection with a live virus or other immune stimulus." (PMID 23056330, 2012). "This infection condition may allow macrophages sufficient time to synthesize pro-IL-1β before cell death occurs." (PMID 22563435, 2012). "Furthermore, we have identified both ROS and potassium efflux (due to stimulation of potassium channel) as the intracellular signal essential for triggering inflammasome activation and IL-1β production during infection." (PMID 22295065, 2012). "At 12 h and 24 h post-infection, IL-1β levels in the medium supernatant were measured by ELISA." (PMID 22295065, 2012). "Additionally, we observed that ClpV contributes to IL-1β, IL-6, IL-10, and IL-17 production in murine macrophages in vitro, and using natural host infection, confirmed that changes in IL-17 and IL-6 production in vivo are ClpV-dependent." (PMID 23071529, 2012).
infection (continued). "Thus we conclude IL-1β-dependent control of WNV in the CNS regulates the magnitude of inflammation during acute infection to reduce tissue damage." (PMID 23209411, 2012). "IL-1β levels in the medium supernatant were measured by ELISA at 12 h post-infection." (PMID 22295065, 2012). "Moreover, except for MIP-2, concentrations of TNF-α, IL-1β and KC in the lung homogenates obtained 24 hours after infection with serotype 3S." (PMID 22721450, 2012). "We evaluated TLR2/1L-induced innate immune cytokines e.g. TNF-α, IL-1β, IL-6, IL-23 and IL-12, known to be critical players in the control of Mtb infection, and chemokines such as Gro-α and IL-8 that are required for cell recruitment to the site of infection." (PMID 22866178, 2012). "However, mature IL-1β was only produced in response to infection with ΔSTY bacteria, which is consistent with our previous finding that ExoS interferes with caspase-1 mediated maturation of IL-1β." (PMID 22844497, 2012). "Moreover, the Rac1 inhibitor also reduced the IL-1β production in C. pneumoniae–infected cells when added 2.5 hrs post infection." (PMID 22276187, 2012). "The levels of IL-1β protein expression from infected skin samples at 4 and 24 hrs were evaluated by ELISA and the amount of IL-1β protein at the site of infection in mice adoptively transferred with wt or IL-1β−/− PMN was below the level of detection (data not shown)." (PMID 23209417, 2012). "Surprisingly, we found that neutrophils were the most abundant source of IL-1β during infection." (PMID 23209417, 2012). "For example, we found peak induction of IL-1β and IL-12p40 mRNA in alveolar macrophages occurs on day 3 post-infection in the neonatal bRSV model, whereas IL-6 mRNA was higher at day 5 than day 3 of infection." (PMID 23342375, 2012). "Thus we tested the effect of calpain inhibition on IL-1β secretion after infection with Salmonella typhimurium in LPS-treated peritoneal macrophages." (PMID 22563421, 2012). "This was in contrast to IL-1α which was expressed only at low levels throughout the course of infection suggesting that IL-1β may play the predominant role in immunity against WNV." (PMID 23209411, 2012). "The objective of the present study was to determine whether there was an association between polymorphisms of TNF, LTA, IL1B, IL6, IL8, and CCL1 and the infection and severity of the illness caused by the pandemic A/H1N1 in Mexico in 2009." (PMID 23148654, 2012). "We found that WT neurons produced IL-1β as early as 12 hr p.i. after virus challenge and this persisted throughout the course of infection, thus suggesting that neurons might contribute in part to the total IL-1β response in the CNS." (PMID 23209411, 2012). "By 1 hr post H37Rv-infection there was a significant decrease (P<0.001) in the concentration of the cytokines; Rantes, GM-CSF, Eotaxin IL-13, IL-9 and IL-1b." (PMID 22039457, 2011). "This defect in IL-1β production was confirmed in the serum of infected mice at 3 days of infection." (PMID 22174673, 2011). "In mice, IL-1β and IL-23 are produced by dendritic cells upon infection-induced Th-17 cells." (PMID 21858022, 2011). "To assess whether a similar correlation exists in chicken embryo infection, we determined K60, IL-8, IL-1β and IL-10 transcription in the CAM of embryos infected with C. albicans deletion mutants in comparison to their parental strain." (PMID 21603634, 2011). "ΔSPI1 mutants of both serovars invaded approx. 5 times less efficiently than the wild-type strains and despite this, macrophages responded to the infection with ΔSPI1 mutants by increased expression of proinflammatory cytokines IL-1β, IL-8, TNFα, IL-23α and GM-CSF." (PMID 21314975, 2011). "In contrast, TGF-β has also been shown to promote inflammation by inducing chemotaxis in human peripheral blood monocytes, enhancing their ability for transendothelial migration to sites of infection, and up-regulating the transcription of pro-inflammatory cytokines such as IL-1β and TNF-α." (PMID 21884610, 2011).